HIF1A (hypoxia inducible factor 1 subunit alpha)
Diseases named in the same sentence as HIF1A in open-access papers (continued):
Sharing a sentence is not in itself a finding about the gene and the disease.
glioma (continued). "Inhibiting PI3K/Akt/mTOR, Shh, Wnt/β-Catenin, and HIF-1α can reduce the migration ability and drug resistance of tumor cells to improve the prognosis of glioma." (PMID 35935338, 2022). "Next, sphere formation by single CD133-CD15- primary or GL261 glioma cells after HIF1α or HIF2α knockout was detected." (PMID 34976166, 2022). "miR-576-3p was shown to inhibit EMT and the angiogenic properties of hypoxia-treated glioma cells by targeting HIF-1α." (PMID 35205289, 2022). "A recent study using a murine model of glioma has shown that ablation of HIF-1α leads to enhanced animal survival due to a decrease in the migratory abilities of HIF-1α Knockout Tregs." (PMID 35927985, 2022). "Differential biology was also observed within gliomas and leukemias with regards to the effects of IDH mutation on PHDs and HIF-1α activity." (PMID 35198082, 2022). "Sox2 was also highly expressed in glioma, and there was a positive correlation between the HIF1α/HIF2α and Sox2 expression levels." (PMID 34976166, 2022). "The correlation between HIF-1α expression and pathological grade of gliomas suggests that HIF-1α expression should also be increased in response to oncogene activation and/or tumor suppressor gene inactivation during tumor progression." (PMID 36157351, 2022). "This study demonstrates that both HIF1α and HIF2α, as genes upstream of Sox2, regulate the malignant progression of glioma through dedifferentiation." (PMID 34976166, 2022). "Its downregulation in gliomas is controlled by HIF1α via the activation of ZEB2, resulting in cancer cell invasion and anti-angiogenic resistance." (PMID 35205289, 2022). "In conclusion, there was heterogeneity of HIF-1α expression in glioma tissue, and IVIM and R2* Mapping were found to be promising methods for the noninvasive detection of the distribution and expression level of HIF-1α." (PMID 35785202, 2022). "We knocked out HIF1α, HIF2α and Sox2 in glioma cells and cultured them under hypoxic conditions to detect CD133 and CD15 expression." (PMID 34976166, 2022). "Briefly, this study demonstrates that both HIF1α and HIF2α, as genes upstream of Sox2, regulate the malignant progression of glioma through dedifferentiation." (PMID 34976166, 2022). "Western blotting analysis also confirmed high expressions of Sept9 and Hif-1α in glioma tissues and adjacent normal tissues in eight patients, conforming to WHO grade." (PMID 35096204, 2022). "A disorganized and functionally impaired vasculature in glioma can contribute to decreasing D*, and the metabolic demand of tumor cells leads to increased HIF-1α expression." (PMID 35785202, 2022). "Glioma aggressiveness and patient outcomes have also been found to correlate with HIF-1α levels and tenascin C-enriched ECM stiffness." (PMID 36076905, 2022). "This is consistent with previous CGGA statistical results, so the inhibitory effect CA has on glioma cells has a significant relationship with Hif-1α." (PMID 35096204, 2022). "Based on our results, we conclude that the dedifferentiation process is induced under hypoxic conditions via regulation by the HIF1α/HIF2α-Sox2 pathway, which provides new ideal targets for glioma treatment." (PMID 34976166, 2022). "Initial studies proved the inhibition of the accumulation of HIF-1α, one of the most important hypoxia-regulated proteins, by BA under hypoxic conditions in prostate, glioma, endometrial and cervical cancer." (PMID 36611970, 2022). "In accordance, a combinational treatment with Topotecan and Bevacizumab, a humanized monoclonal antibody against VEGF, has been reported to exert antiproliferative function towards glioma cells due to HIF-1α activity reduction." (PMID 35409080, 2022). "A bioinformatics analysis of glioma cohort data showed that HK-II overexpression in gliomas was prognostic with the up-regulation of already known associated markers with tumor progression/recurrence (such as VEGF, CXCL8, and HIF1A)." (PMID 35677429, 2022).
glioma (continued). "In this study, we found satisfactory feasibility for using the noninvasive methods of R2* Mapping and IVIM imaging to detect HIF-1α expression in glioma." (PMID 35785202, 2022). "By using the TCGA and GTEx databases, we found that both HIF1α and HIF2α were highly expressed in glioma tissues." (PMID 34976166, 2022). "Accurate evaluation of HIF-1α levels can facilitate the detection of hypoxia niches in glioma and treatment decisions." (PMID 35785202, 2022). "Different from BMAL1 expression, HIF-1a expression in low-grade glioma tissues differs from that in adjacent peritumor tissues (P < 0.05)." (PMID 34815366, 2021). "miRNAs regulate cancer cell biology including cell proliferation and invasion in glioma and ovarian cancer cells via HIF-1α and MMP9 pathways." (PMID 33919449, 2021). "In accordance with what was previously reported for SFN, we demonstrated that SFX-01 reduced the expression of HIF1α in glioma cells." (PMID 34832864, 2021). "Hypoxia-induced USP22-BMI1 axis accelerates the malignancy and stemness of glioma stem cells by regulating the HIF-1α." (PMID 34753387, 2021). "The expression of HIF-1a in high-grade gliomas was significantly higher than that in adjacent peritumor tissues (P < 0.001) and low-grade glioma (P < 0.01)." (PMID 34815366, 2021). "Simultaneous pH and oxygen-sensitive MRI have revealed higher acidity and higher hypoxia in IDH wt than IDH mutant gliomas, correlating to higher HIF-1α expression and increased proliferation index." (PMID 34073734, 2021). "To illustrate the role of canstatin in glioma-mediated VM formation, we examined the expression of VM-associated factors such as VEGF and HIF-1α, one of the principal drivers of VM in the lentivirally conduced U87 cells overexpressing canstatin." (PMID 34434564, 2021). "We aimed to determine the T-cell exhaustion status in high- and low-HIF1A-expression groups in different grades of gliomas and in paired primary and recurrent tumors." (PMID 34305618, 2021). "As demonstrated in a mouse glioma model, HIF-1α stabilization in Tregs leads to a shift toward FAO and glutaminolysis supported by an upregulation of lipid transporters CD36, SLC27A1 and SLC27A4 and decreased glucose oxidation." (PMID 33532902, 2021). "This study first found that knockdown or overexpression of miR-495-3p can significantly change HIF1A expression level in glioma cells." (PMID 34345216, 2021). "We found that HIF-1α silencing significantly decreased the proliferation rate of the irradiated glioma cells whereas HIF-1α overexpression had the opposite effect, which confirmed the crucial role of HIF-1α in the response to radiotherapy." (PMID 34917504, 2021). "The dynamic effects of OR7E156P and miR-143 on HIF1A levels, glioma cell invasion and proliferation, and HUVEC tube formation were examined under conditions of normoxia or hypoxia." (PMID 34422645, 2021). "The stimulation of HIF-1α and the process of angiogenesis appears to be activated only when hypoxia occurs in IDH1-mutated gliomas." (PMID 34070746, 2021). "HIF-1α knockdown decreased the percentage of viable glioma cells, whereas ectopic expression of HIF-1α had the opposite effect (P > 0.05)." (PMID 34917504, 2021). "The expression of HIF1A was higher in GBM than in lower-grade glioma in the CGGA (p = 0.008) and TCGA (p < 0.001) datasets." (PMID 34305618, 2021). "Other immune checkpoints that are targeted by drugs for clinical use, including B7H3 (CD276) and TIM3 (HAVCR2), were also found to be highly expressed in patients with high-HIF1A-expression gliomas." (PMID 34305618, 2021). "Hypoxia and hypoxia-induced expression of HIF1A play a critical role in glioma development and aggressiveness." (PMID 34422645, 2021). "High HIF1α expression levels in surgically resected glioma tissue are significantly correlated with shorter overall survival." (PMID 34745938, 2021).
glioma (continued). "HIF-1α, indeed, is the main driver of cell response to hypoxia and other critical processes enrolled in glioma transformation and proliferation such as angiogenesis, epithelial to mesenchymal transition, invasiveness, and stemness." (PMID 33672324, 2021). "Through a HIF-1α-dependent way, hypoxia modulates glioma cells secretome, which induces STAT3 phosphorylation and subsequently promotes CSC self-renewal capacity in vitro and in vivo." (PMID 34539584, 2021). "Hypoxia‐inducible factor 1α (HIF‐1α) facilitates the survival, invasion and proliferation of glioma by the release of DLK1 intracellular fragments and nuclear translocation." (PMID 34755451, 2021). "Because HIF-1α was in turn a target for miR-138, this finding explained why H19 affected angiogenesis, migration as well as proliferation of the glioma cells through targeting HIF-1α and affecting VEGF expression." (PMID 34646821, 2021). "Inside the anoxic and in the intermediate area of the glioma tumor mass, the highest level of HIF-1α was observed." (PMID 34422645, 2021). "In conclusion, borneol sensitized glioma cells to radiation by accelerating autophagic cell death through the mTORC1/eIF4E/HIF-1α axis, and should be considered for the treatment of advanced gliomas." (PMID 34917504, 2021). "EGLN3 elaborates the growth-suppressive function by suppression of EGFR signaling, which independent to HIF1α and NF-κB in gliomas." (PMID 34112167, 2021). "We found that the HIF1A overexpression significantly increased cell proliferation, migration, invasion and VM of glioma cells, and reverse the tumor-suppressive effect of miR-495-3p up-regulated." (PMID 34345216, 2021). "Consistent with this, silencing of either mTORC1 or eIF4E significantly decreased the levels of HIF-1α in glioma cells, and increased that of LC3 and Beclin-1." (PMID 34917504, 2021). "Both HIF-1α and HIF-2α are also associated with hypoxia-induced expression of CD133 and knocking down of either HIF-1α or HIF-2α was shown to reduce hypoxia-induced CD133 expression in glioma CSCs." (PMID 34099013, 2021). "In glioma cells, PD-L1 expression was induced under hypoxia condition, and the enhanced PD-L1 expression was abrogated by either HIF-1α knock-down or HIF-1α inhibitor treatment." (PMID 34118979, 2021). "Consistent with this, borneol significantly downregulated HIF-1α, mTORC1 and eIF4E in the irradiated human glioma primary culture cells, and the inhibitory effect of the combination therapy was stronger compared to radiotherapy alone." (PMID 34917504, 2021). "Consistently, miR-143 knockdown within glioma cells dramatically reversed the roles of OR7E156P knockdown in HIF1A, ZEB1, and VEGF expression." (PMID 34422645, 2021). "In glioblastoma, oroxylin A was observed to promote VHL-mediated HIF-1α degradation and limit the HIF-1α-Hh signaling pathway, thus sensitizing glioma cells to temozolomide in vitro and in vivo." (PMID 34575983, 2021). "Up- or down-regulated miR-495-3p expression level in glioma cells to evaluated the the mRNA expression of HIF1A by RT-PCR." (PMID 34345216, 2021). "In a previous study, we found that the natural terpene derivative borneol inhibited HIF-1α in primary glioma cells by regulating the mTORC1/eIF4E pathway, and induced autophagy and apoptosis." (PMID 34917504, 2021). "We found that Cav-1 was an upstream regulator governing the expression of HIF-1α in glioma cells, which suggests a promotive role of Cav-1/HIF-1α/VM axis in glioma development." (PMID 34287575, 2021). "miR-143 inhibition increased HIF1A protein levels, promoted glioma cell invasion and DNA synthesis, and enhanced HUVEC tube formation, whereas OR7E156P silencing partially reversed the cellular effects of miR-143 inhibition." (PMID 34422645, 2021). "A previous study reported that glioma cells with IDH1 mutation produce 2-hydroxyglutarate, which promotes HIF-1α degradation, accompanied by the downregulation of glycolysis-related genes including SLC2A1, PDK1, LDHA, and SLC16A3." (PMID 33627136, 2021).
glioma (continued). "HIF-1α has been proposed to drive glioma progression from low-grade astrocytoma to GB; both protein and mRNA expression have been related to a higher pathological tumor grade and poor prognosis." (PMID 34830491, 2021). "MTORC1 knockdown significantly decreased HIF-1α expression in glioma cells (P < 0.01), and increased that of LC3 and Beclin-1 (P <0.01)." (PMID 34917504, 2021). "In a previous study, we showed that borneol inhibited HIF-1α in primary human glioma cells and rat glioma tissues by targeting the mTORC1/eIF4E pathway, which is also involved in autophagy regulation." (PMID 34917504, 2021). "In our study, we used Hif-1α as the pathological gold standard to evaluate the hypoxia of high-grade glioma and found that there was positive correlation between D-value and Hif-1α." (PMID 35155219, 2021). "Here, we explored the relationship between HIF-1α and PD-L1 expression in glioma, and investigated their clinical significance." (PMID 34118979, 2021). "Rapid proliferation within glioma outstrips their blood supply likely leading to intratumoral necrosis and induction of hypoxia likely involving HIF-1α and HIF-2α overexpression." (PMID 33937253, 2021). "HIF-1α activation promotes glioma cell survival, proliferation and metastasis under hypoxic conditions, and is therefore a promising therapeutic target." (PMID 34917504, 2021). "Taken together, borneol sensitized glioma cells to radiation by targeting the mTORC1/eIF4E/HIF-1α pathway." (PMID 34917504, 2021). "Another similar hub gene Serpin family H member 1 (SERPINH1), also known as HSP47, was proved to promote GBM stem-like cell survival by modulating tumor microenvironment through TGF-β pathway and enhance glioma angiogenesis through HIF1α-VEGFR2 signaling." (PMID 34868960, 2021). "Overexpression of HIF1A can rescued the inhibitory effect of miR-495-3p on the proliferation, migration, invasion and VM formation ability of glioma cells." (PMID 34345216, 2021). "The expression levels of HIF-1α, mTORC1 and eIF4E in glioma tissues was markedly lower in the animals treated with borneol and/or radiation compared to the untreated tumor-bearing group (P<0.05 or P<0.01)." (PMID 34917504, 2021). "We aimed to describe the T-cell exhaustion status of gliomas under different levels of HIF1A expression." (PMID 34305618, 2021). "Studies in GB tissue showed that HIF-1α immunoreactivity is particularly strong in areas surrounding necrosis that is predominantly in the nuclei, while in low-grade gliomas, HIF-1α expression is predominantly located in the cytosol." (PMID 34830491, 2021). "Within gliomas, HIF-1α primarily is localized in pseudopalisading cells around areas of necrosis and in tumor cells infiltrating the brain at the tumor margin." (PMID 34422645, 2021). "Our findings suggest that borneol sensitizes glioma cells to radiation by inducing autophagy via inhibition of the mTORC1/eIF4E/HIF-1α regulatory axis." (PMID 34917504, 2021). "The dynamic effects of the OR7E156P/miR-143 axis on HIF1A levels and glioma cells were subsequently investigated." (PMID 34422645, 2021). "Taken together, it is demonstrated that the effects of miR-210 on transcriptional level of TGF-β1 and malignant behaviors of glioma cells, is independent on the HIF-1α transcriptional activity induced by hypoxia." (PMID 34197482, 2021). "Exosomes containing linc01060 can improve the progression of glioma by regulating MZF1/c‐Myc/HIF‐1α signalling pathway." (PMID 34755451, 2021). "Among these tumors, Glut1- and Hif1a-knockdown (KD) IG27 gliomas showed significantly reduced tumor expansion areas and cell numbers compared to control IG27-diffuse glioma." (PMID 33506198, 2021). "In the peripheral blood of glioma patients, CTCs significantly correlated with the increased expression of HIF-1α in the systemic immune system." (PMID 34763698, 2021). "In contrast, HIF‐1α+ cells were distributed in glioma samples, but their number and staining intensity varied among the samples." (PMID 31960509, 2020).
glioma (continued). "FTL expression positively correlated with HIF1A in glioma tissues and obviously increased in U87 and U251 cells under hypoxia in a time-dependent manner." (PMID 32677981, 2020). "Glioma invasion is promoted in a HIF1α-dependent manner through the expression of lncRNAs H19 and AWPPH." (PMID 33126510, 2020). "It was demonstrated that CXCL8 participates in this cellular process by activating the JAK/STAT1/HIF-1α/Snail signaling pathway in glioblastoma cells, thus promoting glioma progression." (PMID 32456359, 2020). "In patients with glioma, IHC analysis revealed the positive correlation between HIF-1α expression, periostin (POSTN) expression, and the infiltration of TAMs (CD11b+) and M2 type TAMs (CD206+) in tumor sections." (PMID 32486098, 2020). "Hypoxia microenvironment promotes glioma cells aggressive phenotype by upregulating hypoxia-inducible factor (HIF) family.HIF1A is highly expressed in glioblastoma and significantly correlated with IDH1/2 mutation." (PMID 32677981, 2020). "Then the results of IHC staining showed that FTL was positively correlated with HIF1A in glioma tissues." (PMID 32677981, 2020). "The present immunohistochemical analysis revealed upregulation of Prox1 and HIF‐1α in some glioma tissues as well as the differentiation of nestin+ tumor stem cells into LYVE‐1+ lymphatic vessels." (PMID 31960509, 2020). "In summary, we observed up‐regulated co‐expression of Prox1 and HIF‐1α in gliomas as well as the differentiation of nestin+ tumor stem cells into LYVE‐1+ lymphatic endothelial cells that formed lymphatic vessels." (PMID 31960509, 2020). "On the other hand, silencing Beclin-1 significantly decreased the expression of VEGF, MMP2, and HIF-1α in U87-MG glioma cells, leading to a reduction in the length of vasculogenic mimicry (VM) tubes under hypoxic conditions." (PMID 32707662, 2020). "In a glioma mouse model, an ad libitum KD led to significantly reduced HIF-1α and CA IX levels in the tumor." (PMID 31399389, 2020). "It was further discovered that in the human primary cultured glioma cells borneol regulated HIF-1a expression via mTORC1/eIF4E pathway." (PMID 32626528, 2020). "ZEB1 was also found to have an inhibitory transcriptional function by binding to the promoter region of LIF to suppress its expression in glioma cancer stem cells, which inspired us to investigate the role of HIF1α and the ZEB1/LIF axis in hepatic I/R injury." (PMID 32996684, 2020). "Multimodal radiological images, HE, and HIF-1α staining of high-grade glioma (HGG) samples revealed that the peritumoral hypoxic area overlapped with the cytotoxic edema region and directly contacted with normal neurons." (PMID 33110474, 2020). "Because high HIF-1α was regarded as a biomarker of the existence of hypoxia, hypoxia was detected in the parenchyma surrounding glioma lesions in our study." (PMID 33110474, 2020). "Still, cobalt-induced hypoxia in glioma cells resulted in increased expression of ODC1 preceded by HIF1A upregulation." (PMID 32630408, 2020). "We further analyzed the gene dataset of patients with glioma and showed that the levels of HIF-1α were higher in the astrocytoma group (from grade II to GBM) than those in the non-tumor group." (PMID 32823915, 2020). "In mouse glioma models, a KD or caloric restriction induced the reduction of the tumor microvasculature, accompanied by significant reduction of HIF-1α and VEGF receptor 2 levels." (PMID 31399389, 2020). "In our own experience, we were able in another pediatric high-grade gliomas’ study to correlate this low ADC mean value to an hyperexpression of HIF-1α and/or HIF-2α and patient worst outcome." (PMID 33092063, 2020). "In glioma, both HIF-1α and HIF-2α bind directly to the VE-cadherin promoter and increase VE-cadherin expression to promote vasculogenic mimicry." (PMID 32993787, 2020).